SCN8A (sodium voltage-gated channel alpha subunit 8)
Diseases named in the same sentence as SCN8A in open-access papers (continued):
Sharing a sentence is not in itself a finding about the gene and the disease.
absence seizures (7 papers, 2022 to 2025). "Strain dependency of features associated with LoF SCN8A models like absence seizures is also known to occur." (PMID 41151066, 2025). "Cell-type-specific studies have shown that Scn8a loss from cortical excitatory neurons increases seizure resistance, while loss from thalamic reticular nucleus inhibitory neurons can trigger absence seizures through altered thalamocortical synchrony." (PMID 41151066, 2025). "Patients with SCN8A mutations develop seizures with different morphologies, including focal or afebrile generalized tonic–clonic convulsions, infantile spasms, and absence seizures, usually accompanied by psychomotor disorders of various degrees." (PMID 38003469, 2023). "Scn8a encodes the voltage-gated sodium channel, NaV1.6, and mice with reduced NaV1.6 expression have frequent and well-characterized absence seizures, due at least in part to specific hypofunction of inhibitory neurons in the thalamus." (PMID 37014118, 2023). "Indeed, the CST waveform was reminiscent of the spike-wave discharges that are the hallmark of absence seizures, yet also strikingly resembled the seizures observed in Scn8a mutant mice." (PMID 38179821, 2024). "Here, we found network-specific increased oligodendrogenesis and myelination only after the onset of absence seizures in two distinct rodent models (Wag/Rij rats and Scn8a+/mut mice) of generalized epilepsy." (PMID 35501379, 2022).
Tremor (7 papers, 2009 to 2025). An unintentional, oscillating to-and-fro muscle movement about a joint axis. "The Scn8a gene is mutated in at least 11 mouse mutants, which show a range of motor dysfunction including paralysis, dystonia and tremor." (PMID 19737145, 2009). "We report that a novel ENU-induced mouse mutant, Cloth-ears (Scn8aClth), shows hearing loss with peripheral neural auditory impairment as well as paroxysmal motor symptoms and tremor, and that a missense mutation in Scn8a underlies this phenotype." (PMID 19737145, 2009). "Particularly, this is markedly different to a non-lethal Scn8a mutant that shows a tremor: Scn8amed−jo/Scn8amed−jo mice have a marked loss of cerebellar Purkinje cells." (PMID 19737145, 2009).
benign familial infantile seizures (6 papers, 2017 to 2024). "For benign familial infantile epilepsy caused by SCN8A mutation, seizures were easily controlled by mono-therapy." (PMID 28923014, 2017).
Seizure (6 papers, 2017 to 2026). A seizure is an intermittent abnormality of nervous system physiology characterized by a transient occurrence of signs and/or symptoms due to abnormal excessive or synchronous neuronal activity in the brain. "In addition to causing epileptic seizures, SCN8A mutations can affect speech, intelligence, and development in pediatric patients." (PMID 38174099, 2023).
colorectal cancer (5 papers, 2019 to 2024). A primary or metastatic malignant neoplasm that affects the colon or rectum. "SCN8A (Sodium Voltage-Gated Channel Alpha Subunit 8), a member of the gene family encoding sodium channel α subunit, was found to be highly expressed in colorectal cancer tissues and positively correlated with lymph node metastasis of colorectal cancer." (PMID 37198621, 2023). "SCN8A (sodium voltage-gated channel alpha subunit 8), which is related to different types of cancers including colorectal cancer, prostate cancer, breast and some other types of cancer, emerges as an aggressive oncogene and could cause poor prognosis." (PMID 31141819, 2019).
early infantile epileptic encephalopathy type 13 (5 papers, 2019 to 2023). "De novo missense GoF SCN8A mutations, which result in single amino acid alterations in the protein product, are linked to the severe form of early infantile epileptic encephalopathy 13 (EIEE13)." (PMID 38003469, 2023). "Early infantile epileptic encephalopathy Type 13 (also called SCN8A encephalopathy) is caused by mutations of the SCN8A gene encoding the alpha subunit of Nav1.6 channel protein." (PMID 33841294, 2021).
epilepsy syndrome (5 papers, 2022 to 2026). A syndrome that has a characteristic cluster of clinical features and/or lectroencephalographic (EEG) findings that reflect underlying epileptic activity. "Gain-of-function (GoF) variants in human SCN8A generally result in early-onset SCN8A-related epilepsy syndromes (SCN8A-RES)." (PMID 35234610, 2022).
Lennox-Gastaut syndrome (5 papers, 2022 to 2026). Lennox-Gastaut syndrome (LGS) belongs to the group of severe childhood epileptic encephalopathies. "Multiple ASM use in the present study emerged as a significant factor influencing QOL, as for CDKL5 deficiency disorder, Dravet and Lennox-Gastaut syndromes, and SCN8A." (PMID 41533235, 2026). "Mutations in SCN2A and SCN8A, the genes that encode NaV1.2 and NaV1.6, respectively, have been implicated in Lennox-Gastaut syndrome (LGS), another severe childhood epilepsy (Epi4K." (PMID 35689251, 2022). "While an effective dose range for CBD in patients with SCN8A mutations has not yet been established, in a long-term open label trial in patients with DS and Lennox-Gastaut syndrome (GWPCARES, NCT02224573), CBD doses from 2.5 to 20 mg/kg/d were administered." (PMID 35153788, 2022).
paroxysmal dyskinesia (5 papers, 2022 to 2025). Paroxysmal dyskinesia (PD) is a rare heterogenous group of movement disorders manifesting as abnormal involuntary movements that recur episodically and last only a brief time. "For example, both PRRT2 and SCN8A mutations may present with paroxysmal dyskinesia, albeit through different mechanisms (see Section 2.2)." (PMID 37288166, 2023). "It remains to be investigated whether other genes implicated in paroxysmal dyskinesia—such as TMEM151A, SCN8A, and PNKD (see Sections 2.2 and 2.3)—also predispose individuals to the spreading depolarization in the cerebellum." (PMID 37288166, 2023).
prostate carcinoma (5 papers, 2014 to 2024). A carcinoma that arises from epithelial cells of the prostate gland. "EPA reliably attenuated the levels of mRNA for SCN9A and SCN8A in rat prostate cancer cell lines." (PMID 38474148, 2024).
temporal lobe epilepsy (5 papers, 2016 to 2023). A localization-related (focal) form of epilepsy characterized by recurrent seizures that arise from foci within the temporal lobe, most commonly from its mesial aspect. "Finally, examination of human brain tissues reveals decreased CDYL and increased SCN8A in the temporal lobe epilepsy group." (PMID 28842554, 2017). "Finally, examination of human temporal lobe epilepsy (TLE) brain tissues reveals decreased expression of CDYL and increased expression of SCN8A, supporting the important role of CDYL in suppressing epileptogenesis." (PMID 28842554, 2017).
Cerebellar atrophy (4 papers, 2013 to 2023). Cerebellar atrophy is defined as a cerebellum with initially normal structures, in a posterior fossa with normal size, which displays enlarged fissures (interfolial spaces) in comparison to the foliae secondary to loss of tissue. "We show that mice of C57BL/6J strain background with selective disruption of Scn8a in PCs display behavioral traits related to neuropsychiatric abnormalities such as ASDs and anxiety, associated with graded loss of PCs and progressive cerebellar atrophy." (PMID 35557557, 2022). "screened 151 individuals with familial or sporadic ataxia and identified an individual with a variant in SCN8A (p.Pro1719Argfs∗6) leading to a LOF by truncating the C terminal domain, which was associated with early-onset severe chronic ataxia and cerebellar atrophy." (PMID 38251463, 2023).
status epilepticus (4 papers, 2016 to 2025). Status epilepticus is defined as a continuous seizure lasting more than 30 min, or two or more seizures without full recovery of consciousness between any of them. "Patient 7: A 7-year-old girl with a heterozygous SCN8A missense mutation (c.2934C>A; p.Ser978Arg) had seizure onset at 2 weeks, followed by febrile status epilepticus at 2 months, and persistent generalized tonic–clonic seizures." (PMID 41573391, 2025). "In contrast, Scn8a expression is increased in the hippocampus following status epilepticus and amygdala kindling." (PMID 29317669, 2018). "One patient had refractory status epilepticus, due to SCN8A mutation; unfortunately, he did not respond to a combination of drugs that included oxcarbazepine, phenobarbital, lamotrigine, and phenytoin." (PMID 33827647, 2021). "A previous study by Zhu and colleagues demonstrated that Scn8a mRNA expression was significantly increased in the ipsilateral hippocampus for up to 2 months following intrahippocampal KA-induced status epilepticus in rats, and the magnitude of the increase was correlated with the severity of SE10." (PMID 29317669, 2018).
attention deficit-hyperactivity disorder (3 papers, 2022 to 2023). A disorder characterized by a marked pattern of inattention and/or hyperactivity-impulsivity that is inconsistent with developmental level and clearly interferes with functioning in at least two settings (e.g. at home and at school). "Patients harboring loss of function variants of Scn8a exhibit neuropsychological abnormalities including emotional instability, anxiety and attention deficit hyperactivity disorders." (PMID 35557557, 2022).
colon cancers (3 papers, 2019 to 2022). "We have also found that the SCN4A and SCN8A subunits are expressed at significant levels, but their role in colon cancer cell properties such as invasive capacities are not yet identified." (PMID 36612049, 2022).
infantile epilepsy (3 papers, 2023 to 2025). "Patients with GOF variants in SCN2A (i.e., onset before three months) and SCN8A (i.e., onset in the first year) present early with infantile epilepsy with variable severities, while those with LOF variants present later in childhood." (PMID 38540325, 2024).
Sudden unexpected death in epilepsy (3 papers, 2021 to 2024). "Patients with SCN8A mutations also have a high incidence of Sudden Unexpected Death in Epilepsy (SUDEP)." (PMID 38233770, 2024).
Anxiety (2 papers, 2018 to 2022). Intense feelings of nervousness, tension, or panic often arise in response to interpersonal stresses. "We therefore carried out behavioral testing of 6-week-old PC Scn8a mutant mice to assess their anxiety level." (PMID 35557557, 2022). "Our data on the PC-specific KO of Scn8a suggest that the enhanced anxiety-like behaviors in Scn8a heterozygous null mice may be mediated by altered output signaling from the cerebellum." (PMID 35557557, 2022). "Likewise, co-existing anxiety-like behaviors were observed in the Scn8a PC mutant mice." (PMID 35557557, 2022). "Importantly, reducing Scn8a expression in the hippocampus did not lead to increased anxiety levels or impaired learning and memory." (PMID 29317669, 2018).
benign familial infantile seizures-5 (2 papers, 2020 to 2023). "Mutations in SCN8A are also associated with benign familial infantile seizures-5 (BFIS5, OMIM #617080)." (PMID 31841065, 2020).
early infantile epileptic encephalopathy (2 papers, 2017 to 2020). "Mutations of SCN8A are associated with type 13 of early infantile epileptic encephalopathy (EIEE 13) (OMIM #614558)." (PMID 28923014, 2017).
generalized epilepsy (2 papers, 2022 to 2023). Epilepsy that is characterized by generalized seizure types and may have typical interictal and/or ictal EEG findings that accompany generalized seizure types (for example generalized spike-wave). "We next examined whether our click labeling approach in living primary neurons could be used to study the localization of two variants of the human SCN8A gene (T1787P and I1654N) that cause a generalized epilepsy." (PMID 37288813, 2023). "We next quantified oligodendrogenesis and myelin structure in a second, distinct rodent model of generalized epilepsy with absence seizures—Scn8a+/mut mice." (PMID 35501379, 2022).
glioma (2 papers, 2020 to 2024). A benign or malignant brain and spinal cord tumor that arises from glial cells (astrocytes, oligodendrocytes, ependymal cells). "Further sequencing studies identified that SCNA8 was highly enriched in bulk tumour samples, whilst siRNA knock down of SCN8A sodium channel gene conferred reduced viability (55–62% less growth) in glioma stem-like cells (GSC) conferring obvious implications in malignant progression of GSC." (PMID 33096667, 2020).
heart failure (2 papers, 2015 to 2022). Inability of the heart to pump blood at an adequate rate to meet tissue metabolic requirements. "The neuronal Na+ channel isoform Nav1.6, encoded by SCN8A, is upregulated in a rat model of heart failure and was suggested to contribute to INa,late." (PMID 26121051, 2015).
Hypertension (2 papers, 2024). The presence of chronic increased pressure in the systemic arterial system. "With regard to genes encoding Na+ channels, Scn9a was persistently upregulated in the RVLM with the exception of 12 wk, whereas Scn8a and Scn1a appeared to show upregulation in the NTS around the onset of hypertension at 10 and 12 wk." (PMID 38145287, 2024).
melanoma (2 papers, 2014 to 2018). A malignant, usually aggressive tumor composed of atypical, neoplastic melanocytes. "Another sodium channel, the NaV1.6 isoform (encoded by the SCN8A gene) has been found to be expressed exclusively in macrophages derived from human monocytic leukemia and cancer cells from human melanoma but exclusively in intracellular vesicles." (PMID 30158710, 2018).
migraine (2 papers, 2022 to 2024). "Future research probing the role of Scn8a in mediating neuronal excitability in response to migraine triggers could provide significant insights into SFKs-mediated mechanism of photophobia." (PMID 39390364, 2024). "We also identified two novel genes, Scn8a and Atp5α1 that have not been reported previously in models of migraine." (PMID 39390364, 2024).
Myoclonus (2 papers, 2021). Very brief, involuntary random muscular contractions occurring at rest, in response to sensory stimuli, or accompanying voluntary movements. "LoF variants in SCN8A have also been identified in patients with intellectual disability and myoclonus without seizures." (PMID 32880951, 2021).
ovarian carcinoma (2 papers, 2021 to 2023). A malignant neoplasm originating from the surface ovarian epithelium. "In the case of NaV β subunits, RNA sequencing analysis revealed Nav channel expression in 48 ovarian cancer cell lines, showing a reduced expression of SCN8A (NaV1.6) and SCN1B (sodium voltage-gated channel beta subunit 1) in cancer cells." (PMID 37375748, 2023). "We found that ovarian cancer cells generally express lower levels of voltage-gated sodium channels than normal cells and that two voltage-gated sodium channels, SCN8A and SCN1B, were prognostic biomarkers for ovarian cancer overall survival." (PMID 34771603, 2021).
Apnea (1 paper, 2022). Lack of breathing with no movement of the respiratory muscles and no exchange of air in the lungs. "Tonic seizures are a feature of other models of SUDEP; thus, the Scn8a mutant mouse model utilized in this study represents both an ideal clinical and broadly applicable model of SUDEP and seizure-induced apnea." (PMID 36160949, 2022).
arthropathy (1 paper, 2025). Any disorder of the joints. "We suggest testing patients who are negative for common disease‐causing variants in SeLFIE (SCN2A, SCN8A, KCNQ2, PRRT2) for the ANKH c.‐11C>T change, especially if there is evidence for a familial arthropathy." (PMID 40574727, 2025).
brain malformation (1 paper, 2024). "In the probands with brain malformation, which was most common phenotype in our cohort, TUBA1A was the most frequently observed gene, identified in 12 probands, including one possessing both the TUBA1A and SCN8A pathogenic variants." (PMID 39433808, 2024).
cervical intraepithelial neoplasia (1 paper, 2018). "We also explored the expression of SCN8A and NaV1.6 protein in the neoplasia-carcinoma sequence of human cervical tissue, using samples from non-cancerous cervix, low- and high-grade cervical intraepithelial neoplasia and invasive cervical cancer." (PMID 30158710, 2018).
congenital hypothyroidism (1 paper, 2009). A thyroid hormone deficiency present from birth. "Also of note, mice without the functional sodium channel gene SCN8A are somewhat resistant to seizures and children with congenital hypothyroidism have a significantly reduced incidence of febrile convulsions." (PMID 19505305, 2009).
cortical dysplasia (1 paper, 2021). "Surgical pathology revealed non-classified focal cortical dysplasia and nodular heterotopia, and genetic evaluation revealed SCN8A." (PMID 34149382, 2021).
episodic ataxia (1 paper, 2023). "With our report, three major neuronal voltage-gated sodium channel genes (SCN1A, SCN2A, and SCN8A) have now been implicated as causative genes of episodic ataxia." (PMID 38251463, 2023). "Our findings thus expand the clinical spectrum of SCN8A-related neuronal disorders and confirm SCN8A as a gene associated with predominant chronic or episodic ataxia." (PMID 38251463, 2023). "We collected genetic and electro-clinical data of ten individuals from nine unrelated families carrying novel SCN8A variants associated with chronic progressive or episodic ataxia." (PMID 38251463, 2023).
erythromelalgia (1 paper, 2016). A rare neurovascular peripheral pain disorder due to the intermittent blockage of the blood vessels, usually in the lower extremities or hands. "Recently, rare variants of genes other than SCN9a were described in patients with clinically verified erythromelalgia: those genes included SCN10A (Nav1.8), SCN11A (Nav1.9), SCN5A (Nav1.5), SCN7A (Nav2.1), SCN8A (Nav1.6), SCN1B (Nav β1 subunit), SCN3B (Nav β3 subunit), TRPA1, TRPV1, WNK1 and NGFR." (PMID 27598514, 2016).
essential tremor (1 paper, 2009). A relatively common disorder characterized by a fairly specific pattern of tremors which are most prominent in the upper extremities and neck, inducing titubations of the head. "Essential tremor patients show significantly increased occurrence of high-frequency sensorineural hearing loss; however, a recent screen of patients with essential tremor did not detect any variants of SCN8A." (PMID 19737145, 2009).
hearing loss (1 paper, 2009). "It will be intriguing to consider SCN8A as a candidate gene for peripheral neural hearing loss and paroxysmal neurological or neuromuscular disorders in humans." (PMID 19737145, 2009). "However, mutation in Scn8a has never been shown to cause hearing impairment in either mice or humans." (PMID 19737145, 2009).
hereditary ataxia (1 paper, 2023). An instance of an atactic disorder that is caused by an inherited genomic modification in an individual. "Thus, identifying SCN8A variants as pathogenic in individuals with hereditary ataxia may guide treatment and reduce potential harm." (PMID 38251463, 2023).
lung carcinoma (1 paper, 2020). "Besides no record about SCN8A, THPA confirmed a similar tendency for an increased expression of HDAC1, DLG1, EPHB2 and CALB1, while GDNF was not apparently changed in either normal or lung cancer tissues; no data were available for SCN8A." (PMID 32102656, 2020).
optic neuritis (1 paper, 2019). Optic neuritis is inflammation of the optic nerve, the nerve that carries the visual signal from the eye to the brain.The conditionmay cause sudden, reduced vision in the affected eye(s). "We chose to target Scn8a specifically in the retina and optic nerve for studying demyelination and axonal loss since optic neuritis is prominent and well-characterized in EAE mice." (PMID 31722722, 2019).
paroxysmal kinesigenic dyskinesia (1 paper, 2021). "For example, paroxysmal kinesigenic dyskinesia is most commonly associated with variants in PRRT2 but also variants identified in PNKD, SCN8A, and SCL2A1." (PMID 34177764, 2021).